PTPN9 (protein tyrosine phosphatase non-receptor type 9)
Diseases named in the same sentence as PTPN9 in open-access papers:
PTPN9 is named in the same sentence as 27 diseases in open-access papers, as found by Europe PMC text mining. Sharing a sentence is not in itself a finding about the gene and the disease. The quoted sentences say what the papers report.
breast carcinoma (14 papers, 2012 to 2025). "PTPN9 suppresses the growth and invasion of breast cancer cells by negatively regulating HER2 and epidermal growth factor receptor (EGFR) and suppressing STAT3 activation." (PMID 35957898, 2022). "It is upregulated in breast cancer and enhances tumor growth and progression by silencing the protein tyrosine phosphatase, PTPN9 and the tumor suppressor genes FOXO1 and FOXO3a." (PMID 34199293, 2021). "In breast cancer, PTPN9 indirectly inhibits activity of STAT3 and STAT5 through direct dephosphorylation of EGFR and HER2." (PMID 29558404, 2018). "In this study, we found that miR-96 overexpression can promote the proliferation, migration and invasion of breast cancer cells and that PTPN9 reduction can mimic the miR-96-induced cellular phenotypes." (PMID 27857177, 2016). "The correlation between miR-96 and PTPN9 was further examined by evaluating PTPN9 expression levels in two human breast cancer cell lines, MCF-7 and MDA-MB-468, after overexpression or knockdown of miR-96." (PMID 27857177, 2016). "In conclusion, this study demonstrates for the first time that miR-96 possesses oncogenic activity by negatively regulating PTPN9 expression in breast cancer." (PMID 27857177, 2016). "In breast cancer cells, PTPN9 directly dephosphorylates EGFR and ErbB2, attenuating downstream STAT3/STAT5 signaling, suggesting that PTPN9 status could influence responses to EGFR-directed TKIs." (PMID 41275311, 2025). "However, PTPN9 is targeted by miR-613 and miR-96 in cervical cancer, miR-96 and miR-24 in breast cancer, miR-21 in colorectal cancer, and miR-181a-5p in gastric cancer." (PMID 35957898, 2022). "To investigate whether miR-96 may promote breast tumorigenesis by silencing PTPN9, we assessed the role of PTPN9 on cell proliferation, migration, invasion and cell cycle status after overexpression or knockdown of PTPN9 in breast cancer cells." (PMID 27857177, 2016). "Because miR-96 and its target PTPN9 had opposite expression patterns and biological functions in breast cancer cells, it is quite possible that miR-96 may promote breast tumorigenesis by silencing PTPN9." (PMID 27857177, 2016). "Taken together, this study highlights an important role for miR-96 in the regulation of PTPN9 in breast cancer cells and may provide insight into the molecular mechanisms of breast carcinogenesis." (PMID 27857177, 2016). "Thus, PTPN9 was denoted as a target of miR-96 based on both computational predictions and the inverse correlation between miR-96 and PTPN9 protein levels in human breast cancer tissues." (PMID 27857177, 2016). "Consequently, the cells transfected with both miR-96 mimic and PTPN9-overexpression plasmid exhibited a significantly lower proliferation rate, suggesting that miR-96-resistant PTPN9 can attenuate the proliferative effect of miR-96 on breast cancer cells." (PMID 27857177, 2016). "Taken together, these results indicate that miR-96 may regulate the proliferation, migration and invasion of breast cancer cells through a PTPN9-dependent manner." (PMID 27857177, 2016). "Because miRNAs are generally thought to have expression patterns that are opposite to that of their targets, we next investigated whether miR-96 expression is inversely correlated with PTPN9 expression in breast cancer." (PMID 27857177, 2016). "In addition, miR-27a, miR-96 and miR-182 could promote migration and invasion by the regulation of PTPN9 in breast cancer, and PDCD4 in hepatocellular cancer." (PMID 36539739, 2022). "The researches in breast cancer may provide some references for STAT3 regulation by PTPN9 in HCC." (PMID 29558404, 2018). "Further research on miR-96 and PTPN9 may reveal a new avenue for treatment of breast cancer." (PMID 27857177, 2016). "Therefore, modulation of PTPN9 by miR-96 may explain, at least in part, why the upregulation of miR-96 can promote cell proliferation and invasion and tumor growth in breast cancer." (PMID 27857177, 2016).
breast carcinoma (continued). "Finally, we showed that PTPN9 had opposite effects to those of miR-96 on breast cancer cells, suggesting that miR-96 may promote breast tumorigenesis by silencing PTPN9." (PMID 27857177, 2016). "Oncogenic miR-96 was found to be constantly upregulated in breast cancer tissues where it promotes proliferation, migration, and the invasion of cancer cells through silencing the target gene PTPN9 (gene for tyrosine-protein phosphatase non-receptor type 9)." (PMID 35455015, 2022). "miR-24 targets two regulators (tyrosine-protein phosphatase non-receptor type 9 (PTPN9) and receptor type tyrosine protein phosphatase F (PTPRF)) of EGFR activation, thereby promoting metastasis of breast cancer." (PMID 29455658, 2018). "Thus, PTPN9 may be a potential new target for breast cancer therapy." (PMID 27857177, 2016). "Thus, miR-96 and PTPN9 may have opposite effects on cell cycle regulation in breast cancer cells." (PMID 27857177, 2016). "However, most PTPN family members function as tumor suppressors in breast cancer, including PTPN2, PTPN4, PTPN6, PTPN9, PTPN13, PTPN14, and PTPN23." (PMID 35957898, 2022). "PTPN9 may contribute to tumor suppression by dephosphorylation and silencing of EGFR, ErbB2, and STAT3 in breast cancer." (PMID 34199293, 2021). "PTPN9 also directly interacts with STAT3 and mediates its dephosphorylation in breast cancer cells." (PMID 29558404, 2018). "In this study, we showed that PTPN9 protein levels were significantly lower in breast cancer tissues and that PTPN9 had a negative effect on cell proliferation and invasion in breast cancer cells." (PMID 27857177, 2016). "We measured the expression levels of PTPN9 in the same 10 pairs of breast cancer tissues and corresponding noncancerous tissues and found that PTPN9 protein levels were consistently lower in the cancer tissues." (PMID 27857177, 2016). "Furthermore, we explored the molecular mechanisms by which miR-96 contributes to breast cancer progression and identified PTPN9 (protein tyrosine phosphatase, non-receptor type 9) as a direct target gene of miR-96." (PMID 27857177, 2016). "Furthermore, we identified PTPN9 (protein tyrosine phosphatase, non-receptor type 9) as a direct target gene of miR-96 and showed that miR-96 inhibits PTPN9 expression and consequently promotes proliferation, migration and invasion of breast cancer cells." (PMID 27857177, 2016). "In addition, co-transfection of miR-96 mimic and the PTPN9-overexpression plasmid markedly decreased the number of MCF-7 cells that passed through the transwell chamber, indicating that miR-96-resistant PTPN9 is sufficient to reverse the pro-invasion effect of miR-96 on breast cancer cells." (PMID 27857177, 2016). "Protein tyrosine phosphatase, non-receptor type 9 (PTPN9) is a soluble tyrosine phosphatase that attenuates prolactin- and EGF-mediated STAT5 activation, which regulates expression of genes that promote cell survival and proliferation in breast cancer cells." (PMID 27472371, 2016).
type 2 diabetes (9 papers, 2016 to 2026). "This study showed that 1e increases glucose uptake and suppresses palmitate-induced insulin resistance in C2C12 myotubes via PTPN9 inhibition; thus, it is a promising therapeutic candidate for treating type 2 diabetes." (PMID 35409287, 2022). "More specifically, PTPs such as PTPN1, PTPN2, PTPN9, PTPN11, PTPRF, and DUSP9 are associated with the pathogenesis of type 2 diabetes, as they negatively modulate insulin signaling and induce insulin resistance." (PMID 35409287, 2022). "Some PTPs, such as PTPN1, PTPN9, PTPN11, PTPRF, PTPRS, and dual specificity phosphatase 9 (DUSP-9), lead to type 2 diabetes associated insulin resistance through antagonism of insulin action." (PMID 33799458, 2021). "Together, these findings suggest that selective inhibition of PTP-1B and PTPN9 could offer new therapeutic targets for type 2 diabetes." (PMID 39682729, 2024). "Related studies indicate that linoleic acid is a multi-target inhibitor of PTPN1, PTPN9, and PTPN11, potentially exerting an anti-diabetic effect to prevent type 2 diabetes." (PMID 41554047, 2026). "Several PTPs, such as PTPN1, PTPN2, PTPN9, PTPN11, PTPRS, and DUSP9, disrupt insulin signaling and trigger type 2 diabetes, indicating that PTPs are promising drug targets for the treatment or prevention of type 2 diabetes." (PMID 35204821, 2022). "Several protein phosphatases, such as PTPN9, DUSP9, and PTPN11, have been identified as AMPK-related targets for type 2 diabetes." (PMID 35563411, 2022). "Inhibition of the megakaryocyte protein tyrosine phosphatase 2 (PTP-MEG2, also named PTPN9) activity has been shown to be a potential therapeutic strategy for the treatment of type 2 diabetes." (PMID 33799458, 2021). "Some PTPs, such as PTPN1, PTPN2, PTPN9, PTPN11, PTPRS, and DUSP9, have been shown to attenuate insulin signaling and trigger type 2 diabetes, indicating that PTPs are promising drug targets for the treatment or prevention of type 2 diabetes." (PMID 35204821, 2022). "Diverse PTPs, such as PTPN1, PTPN2, PTPN9, PTPN11, PTPRS, and DUSP9, have been reported to attenuate insulin signaling and trigger type 2 diabetes, indicating that PTPs are promising drug targets for the treatment or prevention of type 2 diabetes." (PMID 35204821, 2022). "In previous studies, chebulinic acid was shown to have an antagonistic effect on type 2 diabetes by inhibiting the protein tyrosine phosphatase non-receptor (PTPN)-11 and PTPN9." (PMID 35055051, 2022).
cervical cancer (5 papers, 2021 to 2025). A primary or metastatic malignant neoplasm involving the cervix. "Inhibition of PTPN9 can improve migration and cell proliferation in gastric cancer and cervical cancer." (PMID 35156900, 2022).
gastric cancer (5 papers, 2017 to 2022). A primary or metastatic malignant neoplasm involving the stomach. "But in cervical, breast, colorectal and gastric cancers, PTPN9 functions as a tumor suppressor with an essential role in suppressing tumor proliferation, invasion and migration." (PMID 35957898, 2022).
lung carcinoma (4 papers, 2022 to 2024). "Among the many predicted targets, seven genes (SOX4, ZEB2, AVL9, PTPN9, RAB22A, ITGB8 and SIX1) that have been reported to play an oncogenic role in lung cancer were further analyzed." (PMID 35287543, 2022).
Insulin resistance (3 papers, 2021 to 2023). Increased resistance towards insulin, that is, diminished effectiveness of insulin in reducing blood glucose levels. "Several protein tyrosine phosphatases (PTPs), particularly PTPN1, PTPN2, PTPN6, PTPN9, PTPN11, PTPRS, and DUSP9, are involved in insulin resistance." (PMID 37374154, 2023). "Compared with DUSP9, PTPN9 knockdown resulted in a greater increase in AMPK phosphorylation, while Brice Emanuelli showed that DUSP9 has a protective effect on insulin resistance by dephosphorylating EAK and JNK, which have been shown to induce insulin resistance." (PMID 35409287, 2022).
breast tumor (2 papers, 2021 to 2022). "It has been also established that PTPN9 stimulated the dephosphorylation of EGFR and ErbB2 in breast tumor cells." (PMID 35156900, 2022).
diabetes (2 papers, 2021 to 2024). "QG was recognized as a dual-target drug compound with an inhibitory effect against PTPN6 and PTPN9, presenting a potential treatment for diabetes in muscle cells." (PMID 38474775, 2024). "This study highlights QG as a potent and novel compound against diabetes that targets both PTPN6 and PTPN9." (PMID 38474775, 2024).
glioma (2 papers, 2015 to 2017). A benign or malignant brain and spinal cord tumor that arises from glial cells (astrocytes, oligodendrocytes, ependymal cells). "We demonstrated that overexpression of PTPN9 reduces EGFR phosphorylation and cooperates with BRAFV600E inhibitor PLX4720 to reduce MAPK and Akt signaling, resulting in decreased glioma cell viability." (PMID 26023796, 2015). "Interestingly, inactivating mutations or recurrent chromosomal deletions incorporating PTPN9 in GBM are not found in the TCGA database via cBioPortal, which suggests that PTPN9 might not be a common tumor suppressor gene in glioma." (PMID 26023796, 2015). "PTPN9 overexpression per se reduces glioma cell proliferation in the absence of BRAF inhibition in our experiments, indicating that PTPN9 may have a global tumor suppressive role." (PMID 26023796, 2015).
hepatocellular carcinoma (2 papers, 2022). A malignant tumor that arises from hepatocytes. "The literature also demonstrated that PTPN9 inhibited tumor progression in hepatocellular carcinoma, thus inhibits the progression of cancer, and mitigates the cell proliferation." (PMID 35156900, 2022).
lung adenocarcinoma (2 papers, 2022). A carcinoma that arises from the lung and is characterized by the presence of malignant glandular epithelial cells. "For example, circMMD_007 promoted the development of lung adenocarcinoma by targeting miR-197-3p to increase protein tyrosine phosphatase non-receptor type 9 (PTPN9) expression." (PMID 35609310, 2022).
astrocytoma (1 paper, 2015). "Further supporting this hypothesis is the two-fold upregulation of PTPN9 expression in BRAFV600E pediatric astrocytoma compared to BRAF wildtype counterparts (p = 0.001)." (PMID 26023796, 2015).
neuroblastoma (1 paper, 2021). Neuroblastoma (NB) is the most common solid, extracranial childhood tumor. "PTPN9 harbors a lipid-binding Sec14 domain that target the enzyme to secretory vesicles, regulating vesicle size and fusion, and PTPN9 has been shown to directly dephosphorylate TrkA in P19 neuroblastoma cells, which would regulate its transport to the plasma membrane." (PMID 34957126, 2021). "Other non-receptor PTPs related with neuroblastoma include PTPN4, PTPN9, and PTPN12." (PMID 34957126, 2021).
Obesity (1 paper, 2022). Accumulation of substantial excess body fat. "Thus, it is possible that the anti-obesity effects of chebulinic acid are caused by the inhibition of PTPN11 and PTPN9." (PMID 35055051, 2022).
tumor (14 papers, 2012 to 2025). "PTPN9 expression was inversely associated with tumor size, and low expression of PTPN9 predicted poor survival in HCC patients." (PMID 29558404, 2018). "High PTPN9 expression correlates with smaller tumor size in iCCA, higher tumor differentiation and lower T stage in pCCA and higher tumor differentiation in dCCA." (PMID 41275311, 2025). "While phosphatases such as PTP1B and SHP2 are recognized modulators of RTK output, evidence for PTPN9 as a tumor suppressor has been largely restricted to metabolic contexts." (PMID 41275311, 2025). "Mechanistically, crystal structure analysis revealed Tyr333 and Asp335 as key PTPN9 residues interacting with IGF1R; mutation of these residues restored IGF1R signaling and abolished the tumor-suppressive effect of PTPN9." (PMID 41275311, 2025). "In further research, we tend to investigate the regulatory roles of miR-197-3p and PTPN9 in the LC tumor growth in vivo." (PMID 35156900, 2022). "But for PTPN9, which appears to be a tumor suppressor, leads to decreased glioma cell viability by reducing the phosphorylation of EGFR and cooperating with BRAF (V600E) inhibitors to restrain MAPK and AKT signaling." (PMID 35957898, 2022). "Our findings agree with those showing that overexpression of PTPN9 induces apoptosis in different tumor cell lines." (PMID 34124069, 2021). "Interestingly, we found that surufatinib treatment inhibited tumor growth, overexpression of PTPN9 exhibited higher inhibit effect, whereas knockout of PTPN9 markedly exacerbated tumor growth." (PMID 41275311, 2025). "PTPN9 exhibits various functions depending on the type of tumor." (PMID 35957898, 2022). "Immunohistochemical evaluation of IGF1R phosphorylation and PTPN9 expression in baseline tumor biopsies may serve as a valuable tool to stratify patients who are most likely to benefit from IGF1R-directed combination therapies, thereby facilitating biomarker-driven clinical trial designs." (PMID 41275311, 2025). "Moving forward, biomarker-guided clinical trials integrating both tumor-intrinsic and microenvironmental cues-particularly IGF1R phosphorylation status and PTPN9 expression-will be instrumental in refining patient selection and optimizing therapeutic benefit." (PMID 41275311, 2025). "Next, tumor tissue microarrays from patients were analyzed for p-IGF1RY1165/1166, followed by correlation analysis with PTPN9 expression." (PMID 41275311, 2025). "The expression level of PTPN9 was significantly reduced in HCC tumor tissues compared to non-tumorous tissues." (PMID 29558404, 2018).
cancer (7 papers, 2016 to 2025). A tumor composed of atypical neoplastic, often pleomorphic cells that invade other tissues. "We identified miR-96-5p which possesses dual anti-apoptotic/pro-angiogenic functions by targeting caspase-9 in cancer cells and the anti-angiogenic tyrosine-phosphatase PTPN9, highly downregulated in the choroid." (PMID 31188886, 2019).
neurodevelopmental disorder (1 paper, 2021). A behavioral and cognitive disorder with onset during the developmental period that involves impaired or aberrant development of intellectual, motor, or social functions. "PTPN9 belongs to the protein tyrosine phosphatase family, which is involved in numerous important biological processes, and PTPN9 knockout mice show severe neurodevelopmental disorders." (PMID 33630843, 2021).
PTPN9 also shares sentences with these, for which no sentence is quoted: colorectal cancer (1 paper); head and neck cancer (1); Hyperglycemia (1); leukemia (1); melanoma (1); non-small cell lung carcinoma (1); pancreatic ductal adenocarcinoma (1); pancreatitis (1); primary open-angle glaucoma (1); prostate carcinoma (1).